CYBA (cytochrome b-245 alpha chain)
Description:
Subunit of NADPH oxidase complexes that is required for the NADPH oxidase activity that generates, in various cell types, superoxide from molecular oxygen utilizing NADPH as an electron donor. Subunit of the phagocyte NADPH oxidase complex that mediates the transfer of electrons from cytosolic NADPH to O2 to produce the superoxide anion (O2(-)). In the activated complex, electrons are first transferred from NADPH to flavin adenine dinucleotide (FAD) and subsequently transferred via two heme molecules to molecular oxygen, producing superoxide through an outer-sphere reaction. Activation of the NADPH oxidase complex is initiated by the assembly of cytosolic subunits of the NADPH oxidase complex with the core NADPH oxidase complex to form a complex at the plasma membrane or phagosomal membrane. This activation process is initiated by phosphorylation dependent binding of the cytosolic NCF1/p47-phox subunit to the C-terminus of CYBA/p22-phox. Aassociates with NOX3 to form a functional NADPH oxidase constitutively generating superoxide.
Synonyms: p22phox; p22-PHOX; CGD4
Tractability: Small molecule: a structure with a bound ligand is known. Antibody: UniProt places it where antibodies can reach, with high confidence; its Gene Ontology location is reachable by antibodies, with high confidence; UniProt predicts a signal peptide or a membrane-spanning region. PROTAC: UniProt records ubiquitination sites on it; ubiquitination databases record sites on it; its protein half-life has been measured.
Target class: Transmembrane 1-electron transfer carriers; Transporter
Safety:
Unwanted effects reported when the protein is acted on. In parentheses: how it was acted on, where the effect was seen, and who reports it.
cardiotoxicity (source: ClinPGx)
longer overall and event-free survival time (source: ClinPGx)
shorter overall and event-free survival time (source: ClinPGx)
side effects (source: ClinPGx)
Gene: Protein-coding gene on chromosome 16 (88,643,275 to 88,651,083, reverse strand). Ensembl gene ENSG00000051523.
Subcellular location: Cell membrane
Pathways (Reactome):
Signal Transduction: RAC1 GTPase cycle; RAC2 GTPase cycle; RAC3 GTPase cycle; RHO GTPases Activate NADPH Oxidases; VEGFA-VEGFR2 Pathway
Immune System: Cross-presentation of particulate exogenous antigens (phagosomes); Neutrophil degranulation; ROS and RNS production in phagocytes
Cellular responses to stimuli: Detoxification of Reactive Oxygen Species
Disease: WNT5:FZD7-mediated leishmania damping
Gene Ontology:
Molecular function: electron transfer activity; protein binding; protein heterodimerization activity; SH3 domain binding; superoxide-generating NAD(P)H oxidase activity; heme binding
Biological process: cytochrome complex assembly; inflammatory response; innate immune response; positive regulation of defense response to bacterium; positive regulation of interleukin-6 production; positive regulation of phagocytosis; positive regulation of reactive oxygen species biosynthetic process; positive regulation of toll-like receptor 2 signaling pathway; positive regulation of tumor necrosis factor production; respiratory burst; superoxide anion generation; superoxide metabolic process; hydrogen peroxide biosynthetic process; smooth muscle hypertrophy; cellular response to angiotensin; cellular response to gamma radiation; cellular response to glucose stimulus; cellular response to L-glutamine; cellular response to mechanical stimulus; cellular response to phorbol 13-acetate 12-myristate; cellular response to tumor necrosis factor; negative regulation of glomerular filtration by angiotensin; positive regulation of blood pressure; positive regulation of cell growth; positive regulation of endothelial cell proliferation; and 8 more
Cellular component: membrane; NADPH oxidase complex; plasma membrane; endoplasmic reticulum membrane; phagocytic vesicle membrane; secretory granule; specific granule membrane; tertiary granule membrane; apical plasma membrane; cytoplasm; dendrite; endosome; focal adhesion; neuronal cell body; perinuclear endoplasmic reticulum; stress fiber
Genetic constraint (gnomAD): Loss-of-function variants: 24 observed, 19.32 expected, observed/expected ratio (o/e) 1.24, 90% interval 0.9 to 1.73. The synonymous counts are far from expectation, so gnomAD's model fits this gene poorly and the ratio says little. Missense variants: 344 observed, 240.72 expected, observed/expected ratio (o/e) 1.43, 90% interval 1.31 to 1.56. Synonymous variants: 164 observed, 106.03 expected, observed/expected ratio (o/e) 1.55, 90% interval 1.36 to 1.76.
Homologues: Orthologues: rat Cyba (89% identical), mouse Cyba (87% identical), dog CYBA (85% identical), pig CYBA (82% identical), guinea pig CYBA (82% identical), tropical clawed frog cyba (69% identical), chimpanzee CYBA (68% identical), macaque CYBA (66% identical), zebrafish cyba (55% identical).
Diseases named in the same sentence as CYBA in open-access papers:
CYBA is named in the same sentence as 169 diseases in open-access papers, as found by Europe PMC text mining. Sharing a sentence is not in itself a finding about the gene and the disease. The quoted sentences say what the papers report.
chronic granulomatous disease (33 papers, 2006 to 2025). Chronic granulomatous disease (CGD) is a rare primary immunodeficiency, mainly affecting phagocytes, which is characterized by an increased susceptibility to severe and recurrent bacterial and fungal infections, along with the development of granulomas. "Germline variants in CYBA are associated with autosomal recessive chronic granulomatous disease, characterized by the failure of activated phagocytes (neutrophils and macrophages), to generate enough superoxide to accomplice intracellular killing of pathogens." (PMID 35158942, 2022). "A 30-month-old girl with an autosomal recessive form of chronic granulomatous disease (CYBA gene mutation affecting p22phox protein) had invasive aspergillosis causing pericarditis, pulmonary abscess, and central nervous system involvement." (PMID 28168067, 2017). "This may reflect a founder effect due to high consanguinity and inbreeding in the Egyptian population, as previously reported in variants in other genes such as CYBA c.295_301del causing chronic granulomatous disease (CGD)." (PMID 38578558, 2024). "Notably, CYBA expression in SLE LDGs was comparable to levels observed in chronic granulomatous disease (CGD) patients, a condition associated with severely impaired Nox activity." (PMID 41279038, 2025). "Mutations in the five structural genes (NCF1, NCF2, NCF4, CYBA, CYBB) are associated with chronic granulomatous disease (CGD), a condition characterized by impaired production of reactive oxygen species (ROS)." (PMID 37533075, 2023). "Chronic granulomatous Disease (CGD) is a rare innate immunodeficiency disorder caused by mutations in one of the six genes (CYBA, CYBB, NCF1, NCF2, NCF4, and CYBC1/EROS) encoding the superoxide-producing nicotinamide adenine dinucleotide phosphate (NADPH)—oxidase complex in phagocytes." (PMID 33746979, 2021). "Mutations in CYBA, which encodes p22phox, cause chronic granulomatous disease (CGD, MIM: 233690)." (PMID 32081864, 2020). "One patient was diagnosed with chronic granulomatous disease (CGD) following an abnormal NBT test, which led to the identification of a pathogenic CYBA mutation." (PMID 40426715, 2025). "In humans, mutations in genes forming the Nox2 complex (CYBB, CYBA, NCF1,2,4) cause chronic granulomatous disease (CGD), a rare inherited immunodeficiency syndrome." (PMID 30274229, 2018). "In particular, Nox2 oxidase function deficiency in phagocytes due to genetic variants (CYBB, CYBA, NCF1, NCF2, and NCF4) has been recognized as a direct cause of chronic granulomatous disease (CGD), an inherited immune disorder." (PMID 29867559, 2018). "CYBA expression was reduced in SLE LDGs (n=11) compared to SLE NDGs and HCs (n=6), with levels resembling those in chronic granulomatous disease neutrophils." (PMID 41279038, 2025). "Studies of mutations causing human chronic granulomatous disease show that mutations in NCF1, CYBB, CYBA, or NCF2 lead to a complete lack of function of the NOX complex." (PMID 17897462, 2007). "Loss-of-function mutations in essential components of the NADPH oxidase including cytochrome b-245, α polypeptide CYBA, cytochrome b-245, β polypeptide (CYBB), and neutrophil cytosolic factor (NCF) 1 and 2 result in chronic granulomatous disease (CGD)." (PMID 35192551, 2022).
Hypertension (23 papers, 2011 to 2025). The presence of chronic increased pressure in the systemic arterial system. "Several variants, including PRKG1 rs1904694, CYP4A11 rs1126742, and CYBA rs4673, demonstrated associations with increased hypertension susceptibility." (PMID 41573461, 2025). "Recently, it has been reported that the A930G and C242T polymorphisms within p22phox (CYBA) gene are involved in the pathogenesis of hypertension." (PMID 24349292, 2013). "Recently, more studies have focused on the association of the CYBA A930G and C242T polymorphisms with hypertension." (PMID 24349292, 2013). "After adjustment for risk factors, including sex, age, body mass index, type 2 diabetes, hypertension, hyperlipidemia, and smoking, a significant effect on the survival was observed only for CYBA gene A allele carrier-state in the 10-year follow-up (HR = 2.84, 95% CI = 1.15–7.02, p = 0.02)." (PMID 36421822, 2022). "Considering that CYBA variants have been widely studied in cardiovascular diseases, including coronary heart disease and hypertension, which are tightly associated with increased levels of ROS, RAC1 rs10951982 may also play a part in inducing oxidative stress." (PMID 29342889, 2018). "Four SNPs (PRKG1/rs1904694 and rs7897633, CYP4A11/rs1126742, and CYBA/rs4673) were still significantly associated after Bonferroni correction (P < 0.0007) adjusted for age, sex, fasting blood glucose, total cholesterol, salt-eating habit, physical activity, and hypertension." (PMID 34671380, 2021). "Until today, the CYBA gene ∗49A>G polymorphism was not related to hypertension; however, other CYBA gene SNPs, namely, -930A>G and -675A>T, were previously associated with this phenotype." (PMID 27314008, 2016). "Other tested parameters such as serum lipid levels, age, gender, a familial history of CAD, hypertension and diabetes mellitus did not correlate with genotypic variants of the CYBA gene polymorphism (data not shown)." (PMID 24477591, 2014).
diabetes (20 papers, 2010 to 2024). "Specifically, five genes—ATF4, ATP1A1, B2M, CYBA, and PRNP—emerged with the highest inference scores in the context of T2D and Diabetes Mellitus, suggesting that these genes play critical roles in the molecular mechanisms underlying these conditions." (PMID 39926598, 2024).
atherosclerosis (14 papers, 2009 to 2026). A disease characterized by the build-up of fatty material and calcium deposition in the arterial wall resulting in partial or complete occlusion of the arterial lumen. "Combined with a higher superoxide production also verified in the presence of genotype CC of the CYBA gene, this interaction exacerbates oxidative damage and further favors atherosclerosis, justifying the observed rise in risk." (PMID 38899268, 2024).
coronary artery disease (10 papers, 2012 to 2022). "In the present study we showed that the −930G allele carrier state of the CYBA −930A>G polymorphism is associated with premature coronary artery disease." (PMID 24477591, 2014). "The CYBA gene ⁎49A>G polymorphism modifies the risk of coronary artery disease." (PMID 27314008, 2016). "In the present work, we tried to analyze a possible association between the −930A>G polymorphism and coronary artery disease and to analyze potential interactions of CYBA alleles and traditional risk factors of atherosclerosis and CAD." (PMID 24477591, 2014).
Hyperglycemia (7 papers, 2011 to 2023). An increased concentration of glucose in the blood. "In HMVEC, gene expression of SOD1 and SOD2 (non-significant) simultaneously increased with O2 ̅ levels, and CYBA (non-significant), NOX1, and NOX4 expression during hyperglycemia." (PMID 24093550, 2013).
Obesity (7 papers, 2014 to 2024). Accumulation of substantial excess body fat. "The second one, CYBA rs12709102, is part of the microbicidal oxidase system of phagocytes that has also been related to CAD, the thickness of the carotid intima media, and as a direct indicator of atherogenicity and obesity, validating our observations in part." (PMID 37372394, 2023).
endothelial dysfunction (6 papers, 2012 to 2024). In vascular diseases, endothelial dysfunction is a systemic pathological state of the endothelium (the inner lining of blood vessels) and can be broadly defined as an imbalance between vasodilating and vasoconstricting substances produced by (or acting on) the endothelium. "In this vein, we have shown for the same subgroup of postinfarction patients, risk associations connected with thrombogenesis using the A387P polymorphism of THBS4 (thrombospondin-4); for oxidative stress, a major cause of endothelial dysfunction, the C242T polymorphism of CYBA (p22phox)." (PMID 22991685, 2012).
pancreatic cancer (6 papers, 2012 to 2021). "The Immune phagocytosis pathway with the tumor suppressor CYBA gene, which regulates the immune system cells and autophagy through phagocytic clearance, have not received enough attention in the existing pancreatic cancer research literature." (PMID 24565114, 2014).
prostate carcinoma (5 papers, 2017 to 2021). A carcinoma that arises from epithelial cells of the prostate gland. "We found that hypermethylation of COL4A6, CYBA, LINC01341, and RHCG was highly prostate cancer-specific, suggesting particularly promising diagnostic potential for these genes." (PMID 28052017, 2017).
breast carcinoma (4 papers, 2016 to 2025). "The present study was aimed to examine the importance and association of the functional polymorphisms of CYBA gene (-930 A/G and 242 C/T) with the oxidative stress in breast cancer (BC) development and progression." (PMID 30310735, 2018). "We further have analysed the haplotype frequencies with respect to CYBA gene polymorphisms in association with risk of breast cancer." (PMID 30310735, 2018). "Further, MDR analysis with respect to CYBA gene polymorphism has shown that 242C/T polymorphism was the best single locus model with a significant risk for breast cancer." (PMID 30310735, 2018). "We have performed a case-control study on 300 breast cancer patients and 300 healthy individuals as controls to examine the role of CYBA gene -930 A/G and 242 C/T single nucleotide polymorphisms (SNPs) using As-PCR and PCR-RFLP assays and its association with OS as measured by plasma MDA levels." (PMID 30310735, 2018).
melanoma (4 papers, 2016 to 2018). A malignant, usually aggressive tumor composed of atypical, neoplastic melanocytes. "CYBA has been reported to be associated with melanoma through DNA hypermethylation during tumor progression." (PMID 28938548, 2017). "Methylation of CYBA has been previously associated with the progression of melanoma." (PMID 28412973, 2017). "CYBA also displays increased methylation in several invasive cell lines in malignant melanoma." (PMID 28938548, 2017). "After adjusting for these risk factors, rs1049255 (CYBA), rs4673 (CYBA), rs8031 (SOD2), and rs2536512 (SOD3) were no longer associated with melanoma risk in all three models (p > 0.00238)." (PMID 29342889, 2018).
metabolic syndrome (4 papers, 2012 to 2023). A cluster of metabolic risk factors for CARDIOVASCULAR DISEASES and TYPE 2 DIABETES MELLITUS. "CYBA mutation or p22phox expression was closely related to insulin resistance in metabolic syndrome by affecting oxidative stress." (PMID 35173708, 2021). "In the present study, we studied the difference in susceptibility to metabolic syndrome in terms of C242T polymorphism of the CYBA gene, taking account of consumed cigarette amounts." (PMID 22396743, 2012). "We tested the hypothesis that the C242T polymorphism in the CYBA gene is related to the prevalence of metabolic syndrome in a cross-sectional study." (PMID 22396743, 2012).
type 1 diabetes (4 papers, 2011 to 2024). "The functional SNPs -675 T → A in CYBA and rs17883901 in GCLC, probably associated with cellular redox imbalances, modulate the risk for renal disease in the studied population of type 1 diabetes patients." (PMID 21962117, 2011). "In the current study, the presence of at least one A allele in -675 T → A SNP and at least one T allele in rs17883901 located, respectively, at the promoter region of the CYBA and GCLC genes modulate the risk for decreased GFR in type 1 diabetes patients even after adjusting for other risk factors." (PMID 21962117, 2011). "Similarly, polymorphisms in the CYBA gene that encodes the p22phox regulatory subunit of NOX was associated with elevated systemic oxidative stress and increased incidence or progression of DKD in individuals with type 1 diabetes." (PMID 39342285, 2024). "Frequency of CYBA - 657 T → A (unregistered), GCLC - 129 C → T (rs17883901) and GPX3 - 65 T → C (rs8177412) polymorphisms in type 1 diabetes patients and non-diabetic control subjects." (PMID 21962117, 2011).
asthma (3 papers, 2012 to 2025). "Briefly, an enhanced production of ROS by blood neutrophils, monocytes, and eosinophils found in asthma can be explained by the effects of functional polymorphisms in the gene encoding p22 phox subunit (CYBA) of NADPH oxidase." (PMID 24895604, 2014). "In particular, we confirmed a potential role in the pathogenesis of asthma for CYBA and CAT genes that was associated with asthma in Czech and Canadian populations, respectively." (PMID 24895604, 2014). "In contrast, polymorphism 640A>G of the CYBA gene showed a relationship with asthma risk only in women." (PMID 24895604, 2014).
liver disease (3 papers, 2016 to 2022). "We then determined the genotypes in each group for CYBA-rs4673, NCF4-rs1883112, NOX4-rs1836882, rs3017887, SOD2-rs4880, and GCLM-rs41303970, and evaluated the association between these variants and HBV-induced liver diseases." (PMID 31969899, 2019).
tuberculosis (3 papers, 2006 to 2023). A chronic, recurrent infection caused by the bacterium Mycobacterium tuberculosis. "Our study aimed to investigate the association of CYBA polymorphisms with susceptibility to tuberculosis." (PMID 27901128, 2016).
allergic asthma (2 papers, 2014 to 2016). A asthma with a basis in a pathological type I hypersensitivity reaction. "On the contrary, the hierarchical cluster analysis of the MDR data in women showed that the CYBA 640A>G, GPX4 C718T, and PON2 S311C gene polymorphisms have a strong synergistic interaction effect on the risk of allergic asthma." (PMID 24895604, 2014).
cervical cancer (2 papers, 2017 to 2023). A primary or metastatic malignant neoplasm involving the cervix. "However, CYBA’s involvement has been previously verified in cervical cancer, and the T allele has been associated with reduced O2- generation in the phagocytic respiratory burst." (PMID 37891885, 2023).
colorectal cancer (2 papers, 2022). A primary or metastatic malignant neoplasm that affects the colon or rectum. "Whole-genome sequencing and bioinformatics analysis on unique colorectal cancer families revealed two attractive candidate predisposition genes, CYBA and TRPM4, each with a loss-of-function variant." (PMID 35158942, 2022).
inflammatory bowel disease (2 papers, 2022 to 2024). A spectrum of small and large bowel inflammatory diseases of unknown etiology. "Germline CYBA variants are associated with early onset inflammatory bowel disease, supported with experimental evidence on loss of intestinal mucus barrier function due to ROS deficiency." (PMID 35158942, 2022). "Germline CYBA variants have been associated with early onset inflammatory bowel disease." (PMID 35158942, 2022). "An important clue about the mechanism of action of CYBA in inflammatory bowel disease was recently shown in CYBA mutant mice which generated low intestinal ROS." (PMID 35158942, 2022).